STAT3 (signal transducer and activator of transcription 3)
Diseases named in the same sentence as STAT3 in open-access papers (continued):
Sharing a sentence is not in itself a finding about the gene and the disease.
tumor (continued). "Further study is being conducted to find the detailed signaling mechanism for R2016 induced immunogenic cell death of tumor cells, although as shown here, R2016 induced apoptotic tumor cell death may in part be through the inhibition of STAT3 and STAT5 phosphorylation." (PMID 28282460, 2017). "In contrast, STAT3 deficiency had no impact on tumour development in CD8−/− animals." (PMID 28276425, 2017). "Interestingly, IL-17A can promote tumor growth through an IL-6/STAT-3 signaling pathway." (PMID 28402963, 2017). "Accumulating evidence supported that activated STAT3 might be a target for anti-tumor treatment." (PMID 28720093, 2017). "Moreover, we also found that treatment with nifuroxazide could inhibit the expression of p-Stat3 in CT26 tumor tissues." (PMID 28055016, 2017). "Studies with transgenic mice expressing the HPV8 early region under the K14-promoter have provided evidence that epithelial STAT3 activation is necessary for HPV8-driven skin tumorigenesis and this may also apply to human HPV-associated carcinogenesis at other body sites." (PMID 28895886, 2017). "Recent studies further showed that mutation of JAK2 was capable of inducing BCL, and inhibition of JAK2 decreased IgM-induced STAT3 phosphorylation and increased apoptosis of tumor cells in a dose-dependent manner, which suggest that JAK2 could be a target for the treatment of BCL." (PMID 29340070, 2017). "However, STAT3 and pSTAT3 levels remained low until the gastric mucosa reached the tumor stage." (PMID 28061480, 2017). "Therefore, STAT3 can act as an oncogene or a tumor suppressor, depending on tumor tissue." (PMID 28709401, 2017). "Some tumor-promoting cytokines might play a critical role in the development of tumorigenesis, such as nuclear factor kB (NF-kB) and transducer and activator of transcription 3 (STAT3)." (PMID 28815182, 2017). "Therefore, a proper targeted therapy against STAT3 in tumor cells might be a strategy for tumor treatment, avoiding undesirable side effects which may affect physiological functions of mature cells." (PMID 27888618, 2017). "Therefore, acetyl-STAT3 could be a potent target for tumor treatment and several small-molecules that inhibit the acetylation of -STAT3 have been reported." (PMID 29137356, 2017). "Thus, endogenous GM‐CSF from tumor cells could promote PD‐L1 expression via the GM‐CSF/JAK/STAT3 axis." (PMID 28218497, 2017). "We found for the first time that GAC indeed inhibits both constitutive and inducible STAT3 activation leading to the suppression of cell proliferation and down-regulation of various gene products that prevent apoptosis and promote inflammation and metastasis in tumor cells." (PMID 28208828, 2017). "Thus, we hypothesized that STAT3 contributes to tumor invasion and metastasis by regulating CCR1 expression." (PMID 29212252, 2017). "Therefore, STAT3 and related pathways may serve as a target for changing the tumor immunologic microenvironment to benefit cancer immunotherapies." (PMID 28848431, 2017). "STAT3 gene may be a promising target because it is aberrantly activated in a wide variety of human cancers and plays crucial roles in tumor cell proliferation, survival, invasion and tumor-promoting inflammation." (PMID 28709401, 2017). "Il6 deficiency also reduced hepatic mRNA levels of Stat3 target genes (Birc5, Bcl2l1 and Ccnd1), cyclins (Ccna2, Ccnb1, Ccnb2), and markers of proliferation (Mki67) and HCC (Afp) in livers from FGF19-expressing mice, further demonstrating the role of IL-6 in mediating FGF19-driven tumour growth." (PMID 28508871, 2017). "Therefore, to determine whether the STAT3-blocked HCC vaccine-induced anti-tumor immune response was mediated by NK cells, we performed an immunization strategy in nude mice that lack mature T cells." (PMID 29115974, 2017). "In addition, tumor-derived products can activate STAT3 signaling in myeloid cells, which may inhibit DC maturation and the stimulation of MDSC development as well as promote tumor growth." (PMID 28388577, 2017).
tumor (continued). "Thus, the effect of luteolin is highly selective to STAT3 ‘addicted’ tumor cells." (PMID 28182003, 2017). "Moreover, JAK2 activated STAT3 pathway has tumor promoting activity." (PMID 28977839, 2017). "We also found that DHA inhibited STAT3 in blood immune cells and counteracted STAT3 activation by tumor cell-released factors in PBMCs and DCs, suggesting the potential enhancement of the anti-tumor function of multiple immune cells and, in particular, that of DCs." (PMID 28435516, 2017). "STAT3 is a master regulator of several key hallmarks and enablers of cancer including cell proliferation, resistance to apoptosis, metastasis, immune evasion, tumor angiogenesis, epithelial mesenchymal transition (EMT), response to DNA damage, and the Warburg effect." (PMID 27027445, 2016). "In addition, VEGF may also directly promote tumor growth through STAT3 and Wnt signaling and represents, therefore, an interesting target for CRC therapy." (PMID 27148488, 2016). "Thus, biological targeting of STAT3 in tumor cells may not only have synergistic effects by potentiating the function of NK cells and other components of the immune response but also produce inhibitory off-target effects on NK cells in certain cancers." (PMID 27148255, 2016). "Moreover, combination of CDDP and STAT3 has more pronounced effect on tumour growth inhibition." (PMID 27129294, 2016). "Therefore, targeting STAT3 could well reduce tumorigenesis and modulate tumour-induced immunosuppression." (PMID 27435207, 2016). "Thus, STAT3-targeted cancer therapies may have a dual function: direct cytostatic or cytotoxic effects on tumor cells and stimulation of cancer destruction and clearance by the immune system." (PMID 27148255, 2016). "Likewise, CD11c+/IAd+ immature DCs, differentiated in the presence of tumor supernatants, displayed much higher STAT3 DNA binding activity compared to control DCs and were impaired in their ability to stimulate T cell proliferation in an allogeneic mixed lymphocyte reaction (MLR)." (PMID 27148255, 2016). "Furthermore, high expression of phosphorylated STAT3 was observed in tumor tissues." (PMID 26683360, 2016). "Accumulating data showed that STAT3 inhibition could promote the apoptosis of tumor cells." (PMID 26919238, 2016). "In addition, STAT3-driven cytokine expression in tumors induces the secretion of immunosuppressive cytokines and represses proinflammatory cytokine expression, leading toward a dampening of immune responses in the tumor microenvironment." (PMID 27148255, 2016). "In addition to directly function on tumor cells, STAT3 also plays pivotal roles in anti-cancer immunity, not only as a potent negative regulator of T helper 1 (TH1)-cell-mediated inflammation, but also as an important activator of genes that are crucial for immunosuppression." (PMID 27435207, 2016). "Moreover, we verified that IL-23 could maintain the potential tumorigenic of OCSCs in vivo and mediate the self-renewal ability and the formation of tumor in OCSCs by activating the signal pathways of STAT3 and NF-κB." (PMID 27738346, 2016). "Thus, understanding STAT3 signaling is crucial for predicting and overcoming tumor resistance." (PMID 26755645, 2016). "Indeed, the strength and duration of STAT3 activation and the formation of feed-forward signaling loops within the tumor stroma are major determinants of cytokine responses and the arising cellular functions that promote tumor growth." (PMID 27325313, 2016). "Therefore, we speculated that the activation of the JAK/STAT3 pathway might promote the CTC attraction during tumour self-seeding." (PMID 26623559, 2016). "Cytokines, such as IL-6, may then activate STAT3 to promote tumor growth." (PMID 27148488, 2016). "Besides, we also found that treatment with nifuroxazide could inhibit the expression of MMP-2, MMP-9 and p-Stat3 in A375 tumor tissues." (PMID 26830149, 2016).
tumor (continued). "In contrast, high ph-STAT3 tumour cell expression was independently associated with improved CSS (HR 0.64, 95% CI 0.64-0.90, P=0.010) independent of other variables, including nodal status, tumour necrosis, LVI, BVI, CD8+ T-lymphocyte infiltrate, CD138+ plasma cell infiltrate, and tumour budding." (PMID 27769057, 2016). "In addition, STAT3 plays a key role in regulating immune response in the tumor microenvironment." (PMID 26621531, 2016). "Therefore, the aim of the present study was to examine the relationship between total and phosphorylated STAT1 and STAT3 tumour cell expression, components of the tumour microenvironment and survival in a mature cohort of patients with invasive ductal breast cancer." (PMID 27769057, 2016). "Collectively, these data suggest that the expansion of stem-like cancer cells in tumor xenografts from ESE3KD-PrECs was associated with elevation of IL-6 and consequent activation of JAK/STAT3 and that it could be efficiently targeted by JAK/STAT3 inhibitors." (PMID 27732936, 2016). "Therefore, IL-6 and its activated STAT3 pathway may represent effective targets for blocking tumour self-seeding by CTCs." (PMID 26623559, 2016). "Likewise, STAT3-driven PD-L1 expression in tumor cells may dampen antitumor immunity by engaging the PD-1 receptor on the surface of NK cells." (PMID 27148255, 2016). "We have previously shown that STAT3 inhibition results in remodeling of the tumor stroma that is associated with increased drug delivery and cytotoxic therapeutic response of PDAC tumors in an aggressive mouse model of PDAC, further validating STAT3 as a novel and viable therapeutic PDAC target." (PMID 27602757, 2016). "Indeed, TGF-β may for instance promote IL-11 secretion by CAFs, which in turn activates STAT3 and drives the proliferation of tumor cells." (PMID 27148488, 2016). "In addition to the protumor activities affecting cell survival and proliferation, miR-21/STAT3 network could contribute to create an immune suppressive tumor milieu, thus supporting the miRNA role as regulator of drug resistance." (PMID 27349385, 2016). "Molecular profiling of tumor tissue, as well as infiltrating lymphoid and myeloid cells, may be of great value to predict the possible immunologic outcome of treating cancer patients with STAT3 inhibitors." (PMID 27148255, 2016). "These cytokines may in turn activate tumor cell proliferation through STAT3 and NF-κB." (PMID 27148488, 2016). "While fingolimod inhibition of Tregs proliferation may abrogate the suppressive role of these cells in the tumor microenvironment, it has more recently been shown that S1PR1 signaling activates STAT3, resulting in accumulation of Tregs and tumor growth in an orthotopic model of breast cancer." (PMID 27800303, 2016). "In multivariate analysis, high ph-STAT3 tumour cell expression was significantly associated with improved CSS (HR 0.69, 95% CI 0.51-0.95, P=0.030) independent of LVI, BVI, CD68+ macrophage infiltrate, CD8+ T-lymphocyte infiltrate, tumour budding and locoregional treatment." (PMID 27769057, 2016). "Therefore, targeting the IL-6/STAT3 pathway in both tumor cells and their stromal fibroblasts could present great therapeutic approach for more efficient eradication of tumors." (PMID 27248826, 2016). "STAT3 is constitutively active in a significant proportion of human solid tumors and regulates a number of important functions in tumorigenesis, including cell cycle progression, apoptosis, tumor angiogenesis, invasion and metastasis, and tumor cell evasion of immune system." (PMID 27128969, 2016).
tumor (continued). "Similar findings were seen when STAT3 and NF-kB activation was assessed by immunohistochemistry, which also revealed a reduction of cells positive for p-STAT3 Y705 and p-NF-kB/p65 Ser536 in both transformed epithelial cells and tumor infiltrating cells in the lesions of IL-21 KO-Apcmin/+ mice." (PMID 25839161, 2015). "In addition, decreasing STAT3 activation with increasing tumor grade has also been observed." (PMID 26272737, 2015). "Thus, Stat3 activation is effective for tumor cell evasion of cancer therapy." (PMID 26169986, 2015). "Importantly, orthotopic grafts of the established ATRT clones in mice demonstrated that Snail overexpression rescued the tumor-initiating capability of CisR/sh-STAT3 cells, and Snail knockdown partially reduced the tumor-initiating capability of Par/STAT3 cells." (PMID 25638155, 2015). "To investigate the potential downstream targets of STAT3-mediated tumor invasion, we performed RT2 Profiler PCR arrays for gene expression levels of EMT associated factors with three pairs of cells: ATRT-Par vs. ATRT-CisR; Par/Ctrl vs. Par/STAT3; and CisR/sh-Scr vs. CisR/sh-STAT3." (PMID 25638155, 2015). "Moreover, knockdown of STAT3 in TC1 cells reduced tumor growth." (PMID 25595909, 2015). "Furthermore, multiple studies have demonstrated that increased levels of activated STAT3 in patient tumor samples is associated with tumor stage, nodal metastasis and decreased survival, although conflicting reports also exist." (PMID 26272737, 2015). "Hence, the regulatory roles of ERp57 in tumor progression and STAT3 activity are still undefined." (PMID 25605256, 2015). "Thus, the targeting of STAT3 by PIAS3 as a mechanism for tumor inhibition may represent a promising treatment in SCC." (PMID 25573684, 2015). "Notably, Ptenpc−/− tumour cells uniformly expressed nuclear Stat3 at 19 weeks of age, whereas more advanced tumours at 52 weeks of age showed profoundly reduced nuclear Stat3 expression, suggesting that Stat3 expression decreased during PCa progression." (PMID 26198641, 2015). "Thus, p-Stat3 may play a dual role: in support of carcinogenesis in early events and of tumor suppression in late events." (PMID 25607111, 2015). "Indeed, STAT3-dependent tumor transformation usually correlates with enhanced expression of anti-apoptotic and pro-proliferative genes such as Bcl-2, MCL-1, cyclin-D1, and c-myc, which help preventing apoptosis and stimulating tumor growth, migration, and invasion." (PMID 26106584, 2015). "IL-6 might drive STAT3 expression in tumour cells, induce angiogenesis and epithelial-mesenchymal transition and induce differentiation of dendritic cells and macrophages toward tumour promoting cells." (PMID 25889974, 2015). "In addition to its direct importance to tumor cells, it has been demonstrated a major role of paracrine and autocrine IL-6/STAT3 signaling mediated by cells of the tumor microenvironment in facilitating tumor progression and inflammatory cell-mediated transformation." (PMID 26501341, 2015). "However, in preclinical models STAT3 has been reported to play either an oncogenic or suppressive role depending on the genetic background of the tumor system, and it is this variability that has in part complicated the preclinical development of JAK-STAT inhibitors." (PMID 26283544, 2015). "STAT3 is required for expression of DC-SIGN on macrophages that might help tumor progression because these cells releasing IL-10 favor the maintenance of an activated STAT3 in a tumor context." (PMID 26074923, 2015). "Therefore, we investigated whether the contribution of TrkB to tumor metastasis involved EMT induction through activation of the JAK2/STAT3 and PI3K/AKT pathways." (PMID 26515594, 2015). "Prior studies in tumor cells showed that ERα may cross-couple with the JAK/STAT3 pathways." (PMID 26477569, 2015).
tumor (continued). "Considering the critical role of STAT3 signaling in cancer (e.g. regulation of VEGF expression and tumor angiogenesis, regulation of pro-inflammatory cytokines), it is possible that the effect of tocilizumab in vivo is mediated indirectly via blockade of downstream events induced by STAT3 signaling." (PMID 26287605, 2015). "Thus, VEGF may be the main downstream target of STAT3/GIV in the context of IL-17-induced tumor angiogenesis." (PMID 26524953, 2015). "STAT3 is a well-characterized positive regulator of various cell survival and signaling pathways, through activation of transcriptional programs leading to tumor cell proliferation, survival, migration/invasion, metastasis, immune evasion, and tumor angiogenesis." (PMID 26065715, 2015). "Specifically, LLL12 reduces STAT3 phosphorylation, inhibits proliferation, and induces apoptosis in a variety of canine and human cell lines (breast, pancreatic, glioblastoma, osteosarcoma) and inhibits tumor growth and angiogenesis in several murine tumor xenograft models." (PMID 26272737, 2015). "Moreover, STAT3 plays a significant role in tumor survival and therapeutic resistance." (PMID 26550019, 2015). "As STAT3 and Snail are regulators of self-renewal and cancer stem-like properties in several solid tissue cancers, we hypothesized that the STAT3/Snail axis activates cancer stem-like and tumor-initiating properties in ATRT cells." (PMID 25638155, 2015). "It is unknown whether Stat3 mediates RKIP-regulating tumor cell invasion and metastasis." (PMID 25915430, 2015). "Mice lacking Stat3 signalling specifically within KrasG12D-mutant tumour cells not only display increased tumour initiation and tumour cell proliferation but also accelerated malignant progression and ultimately markedly reduced survival compared to mice with intact Stat3 signalling." (PMID 25734337, 2015). "In addition, STAT3 and p14ARF expression was lost in metastasis compared with the primary tumours." (PMID 26198641, 2015). "Therefore, we speculate that Fas signaling promotes the GC cell migration and subsequent tumor metastasis through the STAT3-dependent upregulation of Fascin." (PMID 25992623, 2015). "However, it is not well known whether the anti-tumor effect of FXR involves the regulation of SOCS3 or STAT3." (PMID 26416445, 2015). "Thus, the characterization of Y-P versus S-P STAT3 levels in tumor cells may lead to personalized intervention with respect to STAT3 activity." (PMID 26106584, 2015). "On the contrary, others demonstrated that the tumor microenvironment led to both miRNAs down-regulation and that, according to their capability to target Stat3, their reduction leads to the up-regulation of Stat3 itself and the activation of the Stat3-dependent immunosuppressive cascade." (PMID 25538892, 2014). "Interestingly, recent studies suggest that STAT3 may behave as a tumor suppressor by activating expression of genes known to inhibit tumorigenesis." (PMID 24743777, 2014). "STAT3 has many facets in cancer and may act as tumor promoter and tumor suppressor." (PMID 24473086, 2014). "The biological interaction between STAT3 and β-catenin is obviously complex, but it raises the intriguing possibility that tumours in which both these pathways are activated may be biologically different to tumours in which in only of these pathways is activated." (PMID 25348333, 2014). "Thus, inhibition of neo-angiogenesis by suppressing STAT3 may represent an attractive strategy in preventing or delaying new tumor formation." (PMID 24743778, 2014). "Therefore, our findings suggest that a downregulation of BIS expression could serve as a potential strategy for restricting tumor progression via an induction of senescence through the regulation of STAT3/SKP2/p27 pathway." (PMID 25412315, 2014).